KRAS (KRas proto-oncogene, GTPase)
Diseases named in the same sentence as KRAS in open-access papers (continued):
Sharing a sentence is not in itself a finding about the gene and the disease.
pancreatic cancer (continued). "Pancreatic cancer frequently involves mutations in KRAS, which contribute to the activation of MAPK, and active MAPK influences downstream genes that may play roles in malignant pancreatic cancer." (PMID 30279327, 2018). "Furthermore, we found that the antitumor effect of matrine on pancreatic cancer growth depends on the mutation of the KRAS oncogene." (PMID 29791786, 2018). "The G12 KRAS mutation numbers for each of the four tested samples correlated with the CTC enumeration data, indicating that the captured CTCs, defined by a CK+, CD45−, DAPI+ profile, did indeed carry the KRAS mutation and thus originated from the pancreatic tumor." (PMID 30115931, 2018). "What is more important is that this preferable anti-tumor activity may be turned into specifically individualized targeted therapy for pancreatic cancer due to the up to 90% KRas mutations." (PMID 29467941, 2018). "KRAS mutation has been known as crucial marker for growth and maintenance of pancreatic cancers and targeting the KRAS is inevitable component for realizing precision medicine to pancreatic cancers." (PMID 30419860, 2018). "KRAS mutation has been known as being present in 70~ 95% of pancreatic cancers." (PMID 30419860, 2018). "Activating (oncogenic) mutations in KRAS are present in over 90% of human pancreatic cancers." (PMID 29367463, 2018). "The potent ability of the KRAS mutation to stimulate macropinocytosis may be one of the reasons why it is predominantly mutated in pancreatic cancers." (PMID 31225458, 2018). "Indeed, most pancreatic cancer cases uniformly present with a mutation in the KRAS allele leading to enhanced RAS activation." (PMID 30213082, 2018). "Mutations of KRAS might be used to detect pancreatic cancer in early stage and SMAD4 mutations associate with dismal prognosis of pancreatic neoplasia." (PMID 29423035, 2018). "Interestingly, an additional pancreatic cancer patient with a KRAS mutation had progressive disease, however the mutation was in codon 61 (Q61H)." (PMID 27853997, 2017). "More recently, it was shown that human bladder and pancreatic cancer cells that harbor oncogenic HRAS or KRAS mutations, respectively, display an enhancement of macropinocytosis relative to cancer cells of the same tissue type that express wild-type HRAS or KRAS." (PMID 29085336, 2017). "Among the few pancreatic cancer-related genetic mutations, KRAS is very common." (PMID 28103577, 2017). "Finally, AMCPAC cell lines harbor various and noble KRAS mutations and these are useful resources for pancreatic cancer research when associated with KRAS mutation type." (PMID 28435405, 2017). "Furthermore, with the use of next-generation sequencing, it has been shown that pancreatic cancer has few actionable mutations when KRAS mutations are excluded." (PMID 29152071, 2017). "90% of pancreatic tumors harbor an activating KRAS mutation." (PMID 28415695, 2017). "In addition, looking at the specific type of mutation, the presence of KRAS p.G12V seems to be associated with a decrease in survival of pancreatic cancer patients." (PMID 28801547, 2017). "Previous studies revealed that the combined modality of cytopathology and KRAS mutations detection could improve the sensitivity of the diagnosis of pancreatic cancer." (PMID 27974679, 2017). "Moreover, cancer cells can use YAP to compensate for loss of mutant KRAS as shown in cell lines and mouse models of pancreatic cancer." (PMID 27935819, 2017). "Oncogenic KRAS mutations account for >95% of pancreatic cancer development." (PMID 26988754, 2017). "Bioinformatic analysis of human tumours revealed that several core autophagy genes, including GABARAP, correlate with oncogenic KRAS mutations and poor prognosis in human pancreatic cancer, supporting a potential tumour-suppressive effect of the pathway in Ras-driven human cancers." (PMID 28581519, 2017).
pancreatic cancer (continued). "The examined cell lines represented the half of KRAS mutated pancreatic cancer cell types." (PMID 28957417, 2017). "The large majority of pancreatic cancers display KRAS mutations." (PMID 29156578, 2017). "KrasG12D is required for both the initiation and maintenance processes of pancreatic cancer in mouse models, and was shown to be the most common oncogenic KRAS mutation presented in more than 90% of human PDAC, leading to a dominant and constitutively active form of GTPase." (PMID 28753978, 2017). "Q61L KRAS mutation is also rarely reported in pancreatic cancer or neoplasm." (PMID 28435405, 2017). "In addition, KRAS mutations have been linked to poor prognosis in this entity, again hinting at a possible similarity between pancreatic cancer and CUP." (PMID 27322425, 2016). "Pancreatic ductal adenocarcinoma (PDAC) accounts for more than 90% of all pancreatic cancer cases and activating hotspot mutations in the KRAS gene are present in the majority of them, representing the most frequent but also the earliest genetic alteration that drives pancreatic neoplasia." (PMID 27705932, 2016). "As KRAS mutation is one of the key oncogene drivers linked to aggressiveness in various human malignancies—including lung, colorectal, and pancreas cancers 25, 26—it is plausible that mutated KRAS drives both metastasis and cachexia and, consequently, correlates with poor prognosis." (PMID 27485414, 2016). "We demonstrated that cfDNA KRAS mutations were detectable at the time of diagnosis in the plasma of 20% of pancreatic cancer cases at PDAC hotspot codons (12, 13 and 61); a sensitivity which is more consistent with some studies (between 27 to 36%) than others (between 47 to 81%)." (PMID 27705932, 2016). "In pancreatic cancer, mutations in codon 12 of KRAS occur the most frequently." (PMID 27096871, 2016). "Mutations of the KRAS gene occur in over 90% of pancreatic carcinomas." (PMID 27351226, 2016). "Moreover, constitutively present pS-EphA2 in MDA-MB-231 human breast cancer cells harbouring KRAS and BRAF mutations and Panc-1 human pancreatic cancer cells carrying KRAS mutation was also resistant to PI3K inhibition." (PMID 26158630, 2015). "Seventy-one percent of pancreatic cancer specimens in the COSMIC database harbor KRAS mutations." (PMID 25714017, 2015). "Somatic KRAS mutations frequently occur in lung, colorectal and pancreatic cancers." (PMID 26521233, 2015). "Thus, the here described sensitivity of PDAC cancer cells to ferroptosis suggests an alternative pathway to selectively kill pancreatic cancer cells, especially considering that mutationally-active KRas mutations drive the majority of PDAC." (PMID 26097885, 2015). "Based on these findings, we speculate that the KRAS mutation status may be similar in patient materials and pancreatic cancer cell lines." (PMID 25905463, 2015). "Pancreatic cancer shows the highest frequency of KRAS gene mutations among human cancers." (PMID 26046796, 2015). "There is no information as to whether the Y791F mutation was germline or somatic in this patient, but as KRAS G12D is a very well-described pancreatic cancer-driver mutation, the results strongly indicate a minor/non-pathological role for RET Y791F." (PMID 25425582, 2015). "Whether KRAS mutations are associated with less efficient EGFR-directed targeted therapy in pancreatic cancer patients remains controversial and requires further investigation." (PMID 26046796, 2015). "The vast majority of pancreatic cancers involve gain-of-function mutations in KRAS." (PMID 25699241, 2015).
pancreatic cancer (continued). "Given the high preponderance of KRAS activating mutations in PC (~90%), we hypothesized whether KRAS mutations could be contributing to the high frequency of Cav-1 expression in pancreatic cancer." (PMID 26065715, 2015). "Oncogenic, activating mutations in KRAS initiate pancreatic cancer." (PMID 26452271, 2015). "What is interesting about KRAS mutations is that in pancreatic cancer the most common mutation is one amino-acid substitution in position 12 of the KRAS protein, leading to a glycine (G) to aspartic acid (D) substitution, although other variants, such as G to V are also common." (PMID 25361007, 2014). "PK-8, PCI-35, and MIA PaCa2 are pancreatic cancer cell lines harboring the following gain-of-function mutations of KRAS: G12R in PK-8 cells, G12D in PCI-35 cells, and G12C in MIA PaCa-2 cells, but no mutations in the mutational hotspots of exons 8 and 9 (including codons 201 and 227) of GNAS." (PMID 24498386, 2014). "KRAS point mutation has been long-established as a feature of pancreatic cancer." (PMID 25084836, 2014). "It is mutated in 1/3 of pancreatic cancers with known wild-type KRAS." (PMID 24624093, 2014). "Early KRAS mutation is thought to be the driver for the formation of pancreatic cancer." (PMID 24783207, 2014). "We screened tumors from 171 pancreatic cancer patients for mutations in KRAS and CDKN2A genes." (PMID 23565280, 2013). "The association between pancreatic cancer patient survival and specific sub-types of KRAS mutations could also be due to varying abilities to alter the RAS protein." (PMID 23565280, 2013). "In pancreatic cancer, pathway activation typically occurs by mutation of KRAS, but in uncommon KRAS-wildtype tumors, RAF kinase fusions may provide an alternative route." (PMID 23637631, 2013). "Pancreatic cancer is characterized by near-universal mutations in KRAS." (PMID 24231729, 2013). "In addition to the impact of time to implantation and documentable presence of viable tumor cells on tumorgraft development, is the intriguing possibility that the presence of KRAS mutations influences the take rate of pancreatic tumors in preclinical models." (PMID 24194913, 2013). "KRAS mutations are major factors involved in initiation and maintenance of pancreatic tumors." (PMID 23565280, 2013). "In pancreatic cancer, mutations in KRAS are found in more than 90% of patient samples." (PMID 23197977, 2012). "In pancreatic cancer the KRAS gene is a hotspot for somatic mutations and is frequently mutated." (PMID 23049875, 2012). "In pancreatic cancer, KRAS mutations and NF-κB activation is observed in almost all cases." (PMID 22615799, 2012). "Interestingly, KRAS mutations are frequently detected in the most common precursor lesion to pancreatic cancer, pancreatic intraepithelial neoplasia (PanIN), indicating a potential role for early pancreatic cancer in the disease." (PMID 23197977, 2012). "Point mutations in the KRAS proto-oncogene occur in 83–100% of pancreatic tumors." (PMID 24213498, 2012). "The gene encoding KRAS is frequently mutated in patients with pancreatic cancer which results in a gain-of-function that may contribute to the pathogenesis and progression of this cancer." (PMID 22472349, 2012). "Since the majority of pancreatic adenocarcinomas are associated with KRAS mutations and the pattern of metastasis to the lung of pancreatic carcinoma often mimics bronchioalveolar carcinoma, we feel that KRAS mutational analysis can be a useful adjunct to definitively determine the site of origin." (PMID 23119210, 2012). "Furthermore, KRAS mutations leading to persistent activation of cellular signaling events downstream of EGFR are found in 50–95% of pancreatic cancer samples and render proliferation of tumor cells independent of EGFR." (PMID 24212612, 2011). "This was chosen as a model because pancreatic cancer has a high frequency of KRAS mutation." (PMID 21698197, 2011). "In pancreatic cancer, KRAS mutations are present in virtually all tumors." (PMID 22069497, 2011).
pancreatic cancer (continued). "Pancreatic cancer is among these, with 90% of pancreatic cancers exhibiting KRAS mutations." (PMID 21044336, 2010). "KRAS mutations occur in almost all cases of pancreatic cancer." (PMID 21044336, 2010). "The pancreatic carcinomas show three different types of KRAS mutations: G35A, G34C, and G35T." (PMID 21197450, 2010). "Compared with other KRAS-driver mutations, such as G12-hotspot mutations, the Q61H mutation is rare (according to TCGA occurring in lung, colorectal, and pancreatic cancer in 0.2%, 0.7%, 2.8% of cases, respectively), which may explain why this immunogenic epitope has remained undetected so far." (PMID 40165973, 2025). "This may be related to increased reactive oxygen species (ROS) production and activation of fatty acid synthesis, such as via fatty acid synthetase, and pancreatic cancers with KRAS mutations may be expected to have increased lipid peroxidation from GPX4 inhibition." (PMID 39858464, 2025). "Additionally, KRAS mutations, prevalent in pancreatic cancer, might upregulate AQPs, indirectly contributing to tumor progression through enhanced cell proliferation and survival mechanisms." (PMID 40305202, 2025). "Therefore, we next questioned whether WT KRAS could act as a tumor suppressor and whether loss of WT KRAS drives progression to pancreatic cancer." (PMID 39412982, 2025). "Notably, the pancreatic cancer group had a greater frequency of KRAS gene mutation (83.7% vs. 51.3%, p < 0.001) and a greater prevalence of pancreatitis (18.6% vs. 0.9%, p < 0.001) and pancreatic cysts (6.2% vs. 0.2%, p < 0.001) compared to the nonpancreatic cancer group." (PMID 39640479, 2024). "Nevertheless, in all these studies so far, response rates and duration of response seem to be limited in pancreatic cancer, possibly due to emergence of secondary resistance-mediating oncogenic variants or due to clonal selection of pre-existing alternative oncogenic driver KRAS alterations." (PMID 38892436, 2024). "The present study aims to elucidate the predictive value of short-term serial quantitative assessment of KRAS-mutated ctDNA values at initial first-line chemotherapy to identify a reliable indicator of therapeutic response in patients with treatment-resistant advanced pancreatic cancer." (PMID 38277079, 2024). "However, the contribution of infections to the development and progression of pancreatic cancer is not well understood and a functional relationship between KRAS mutations and viral infections, as an etiological cause of human pancreatic cancer, has never been studied." (PMID 39627248, 2024). "Overall, our findings confirmed the central pathogenic role of KRAS mutations, which are highly abundant in pancreatic cancer, inducing to speculate that such a mutated oncogene may participate in early molecular events toward the progression from normal pancreatic tissues to malignant PDAC." (PMID 38280995, 2024). "Furthermore, we examined whether the universal pegRNA could correct the endogenous KRAS mutations in three types of human cancer cells: two pancreatic cancer cell lines, CFPAC-1 and ASPC-1, and one colon cancer cell line, HCT11627,28." (PMID 37391511, 2023). "Interestingly, nearly 95% of all pancreatic cancers have mutations in the KRAS gene." (PMID 36934248, 2023).
pancreatic cancer (continued). "KRAS (Kirsten rat sarcoma viral oncogene homolog) gene mutation is widespread in tumors and is one of the most frequently mutated oncogenes in various malignancies, including lung, colon, and pancreatic cancers, etc.; it is found in one out of every seven human cancers." (PMID 37110848, 2023). "Similarly, AHNAK2, ARL4C, ASAP2 were all highly expressed in pancreatic cancers, correlated with KRAS G12D mutation and could predict survival in pancreatic cancers." (PMID 35785187, 2022). "These neoantigens may represent diagnostic biomarkers, and several lines of evidence indicate that HLA uLigands may also serve as promising immunotherapy targets, similar to classical neoantigens, as recently described for the KRAS G12D mutation in pancreatic cancer." (PMID 36551517, 2022). "Therefore, we compared the predictive ability of GILncSig with KRAS for survival outcome and found that GILncSig was able to identify pancreatic cancer patients with KRAS mutations who may have a higher mortality rate than the rest of the patients." (PMID 36148233, 2022). "Moreover, KRAS mutation could play a crucial role in pancreatic cancer development in patients with CP in a meta-analysis of 15 studies." (PMID 35365692, 2022). "Thus, KRAS mutations should be important biomarkers in pancreatic cancer." (PMID 36232820, 2022). "Pancreatic cancer is another highly lethal disease for which mortality closely parallels incidence, and the major driver gene KRAS is currently not druggable except for some early responses with Sotorasib treatment in those 1–2% of patients carrying the KRAS p.G12C mutation." (PMID 36139547, 2022). "Furthermore, scatter plot analyses showed significant positive correlations of SET/CIP2A expression with the expression levels of the IEGs (TRIB1, SPRY4, CTGF) and with those of growth-promoting genes (cyclin D1, E2, and PCNA) in KRAS-mutated pancreatic cancers." (PMID 36463234, 2022). "Therefore, targeting KRAS point mutations represents one potential way to treat pancreatic cancer." (PMID 35652096, 2022). "However, FTase inhibitors (FTIs) exhibited disappointing results in clinical trials toward to pancreatic cancer, which mainly possess KRAS mutation, and subsequent research revealed KRAS and NRAS gained alternative modifications by geranylgeranyltransferases (GGTase) in cells treated with FTIs." (PMID 34301278, 2021). "Moreover, the expression level of TFCP2 was higher in pancreatic cancer cells with KRAS mutation." (PMID 34804919, 2021). "First, even though a meta‐analysis of KRAS mutations in pancreatic cancer reported poorer prognosis, the cohorts used in the meta‐analyses included fewer cases with KRAS mutation (60%–70% cases) compared to other studies that usually report a 90% prevalence of KRAS mutations." (PMID 33455072, 2021). "In a parallel study, we found that HEK293T cells with constitutively active RAS (RAS-V12) showed higher HPS expression upon p-STAT3 activation, suggesting that HPS may be downregulated by STAT3 and may contribute to KRAS-mutated pancreatic cancer cell proliferation." (PMID 33801246, 2021). "Moreover, KRAS mutation allele frequency (MAF) from exosomal DNA is significantly associated with disease progression after neoadjuvant chemotherapy in a prospective cohort of potentially resectable pancreatic tumor." (PMID 32974169, 2020). "Interestingly, the authors also demonstrated that the mitochondria-targeted antioxidant MitoQ prevents the development of pancreatic cancer in mice with KRAS mutations, indicating that the oncogenic activity of KRAS requires the generation of mitochondrial ROS." (PMID 31819197, 2020).